ILK (integrin linked kinase)
Diseases named in the same sentence as ILK in open-access papers (continued):
Sharing a sentence is not in itself a finding about the gene and the disease.
renal fibrosis (10 papers, 2011 to 2025). A final common manifestation of a wide variety of chronic kidney diseases characterized by glomerulosclerosis and tubulointerstitial fibrosis. "TGF-β1 regulation of EMT has been suggested to be dependent on integrin-linked kinase (ILK) function during renal fibrosis." (PMID 25949265, 2015). "The keywords of cluster 5 (purple) may be the study of mesangial cells, renal fibrosis, down regulation, microrna, proliferation, biomarker, acute kidney injury, cancer, high glucose, integrin linked kinase, nf kappa b, tgf beta, up regulation." (PMID 40862124, 2025). "Moreover, our previous studies have suggested connective tissue growth factor (CTGF)/integrin-linked kinase (ILK) participated in the renal fibrosis development mediated by AngII." (PMID 25954204, 2015). "Increased ILK activity links to epithelial‐mesenchymal transition production and the progression of renal fibrosis." (PMID 37357686, 2023). "MRTFs are also influencing the expression of all major EMT markers and transcriptional regulators, and all three major EMT pathways delineated for renal fibrosis: TGFβ/Smad, Wnt/β-catenin, and integrin/ILK signaling." (PMID 31057405, 2019). "Among the signaling pathways involved in regulating EMT during renal fibrosis, three turned out to be essential in relaying upstream signals: TGFβ/Smad, Wnt/β-catenin, and integrin/ILK signaling." (PMID 31057405, 2019). "This study finds that FA plays a role in the regulation of renal fibrosis by inhibiting TGF-β-induced renal fibrosis possibly through Smad/ILK/Snail pathway and may lead to possible therapeutic interventions to suppress EMT and renal fibrosis." (PMID 25949265, 2015). "Importantly, inhibition of ILK attenuates renal fibrosis in multiple models of CKD." (PMID 33802083, 2021).
Insulin resistance (9 papers, 2020 to 2026). Increased resistance towards insulin, that is, diminished effectiveness of insulin in reducing blood glucose levels. "The greater sensitivity to insulin of ILK-deficient adipocytes suggests that the presence of this highly conserved intracellular protein is necessary for the development of insulin resistance." (PMID 37383542, 2023). "(2016) used muscle‐specific ILK‐deficient (ILKlox/loxHSAcre) mice to study ILK under diet‐induced muscle insulin resistance." (PMID 36054466, 2022). "Using adipocyte-specific ILK-deficient mice, we aimed to understand the role of ILK in adipose tissue in diet-induced obesity and insulin resistance." (PMID 33647469, 2021). "The pathogenic role of ILK in obesity and insulin resistance was studied in human adipose tissue and adipocyte-specific ILK-deficient mice (ILKlox/loxAdCre)." (PMID 33647469, 2021). "Moreover, hepatocyte-specific ILK deficiency in mice ameliorates high fat diet-induced hepatic insulin resistance." (PMID 37383542, 2023). "Tissue-specific deletion of integrin-linked kinase (ILK), an intracellular adaptor protein of integrin receptor signalling, in skeletal muscle, liver, and adipose tissue ameliorates high fat diet-induced tissue-specific insulin resistance." (PMID 37383542, 2023). "ILK signaling amplifies skeletal muscle and liver insulin resistance in diet-induced obesity in mice but the role of α-Parvin is unexplored." (PMID 41577027, 2026). "Herein, we narrow the focus to the roles of the collagen-integrin-ILK pathway and hyalurona-CD44 pathway as examples of processes involved in obesity-associated insulin resistance in adipose tissue." (PMID 37383542, 2023). "That said, what both these studies seem to confirm is that ILK is an important effector in the integrin nexus that acts as a downstream regulator in diet‐induced insulin resistance." (PMID 36054466, 2022). "Our previous works showed that cKDILK under HFD, where ILK is successfully under-expressed in WAT, are predisposed to gain weight and insulin resistance, and therefore can be considered a better tool than other knockouts for upstream or downstream elements." (PMID 35090553, 2022). "Few recent publications, including ours, have described ILK as a mediator during insulin-resistance and WAT remodeling in cells and mice models." (PMID 35090553, 2022). "We recently described Integrin Linked Kinase (ILK), a scaffold protein recruited by INTB1, as an important mediator of WAT remodeling and insulin resistance." (PMID 35090553, 2022). "We previously demonstrated that short-term HFD administration in mice for 2 weeks allows for the early establishment of obesity and insulin-resistance and for observation of ILK involvement." (PMID 35090553, 2022). "While our current study demonstrated a novel role of adipocyte ILK in adipose function and insulin resistance, it is important to highlight the study's limitations." (PMID 33647469, 2021). "Our results from adipocyte-specific deletion of ILK were consistent with previous studies in muscle and liver, suggesting an important role of the ECM-integrin-ILK pathway in promoting insulin resistance in insulin-sensitive tissues of mice on a HF diet." (PMID 33647469, 2021). "Many previous studies from our group have proven a key role of the ECM-integrin-ILK pathway in the pathogenesis of diet-induced insulin resistance in skeletal muscle and the liver." (PMID 33647469, 2021). "It was also intriguing to see that deletion of ILK specifically in the skeletal muscle, liver, or adipose tissue had beneficial effects on systemic insulin resistance or glucose intolerance." (PMID 33647469, 2021). "Interestingly, cardiac ILK depletion in mice reportedly promotes insulin resistance by increasing the phosphorylation of insulin receptors and decreasing the phosphorylation of AKT in conjunction with decreased GLUT4 transcription." (PMID 38543160, 2024).
Insulin resistance (continued). "Moreover, tissue-specific deletion of ILK in skeletal muscle or liver ameliorated high-fat (HF) diet-induced insulin resistance in C57BL/6 mice in the respective tissues." (PMID 33647469, 2021). "This study determined the role of ILK in adipose function and insulin resistance." (PMID 33647469, 2021). "Our results that ILK increased in vWAT but not sWAT of morbidly obese humans support the hypothesis that ILK in visceral fat plays a pathological role in obesity-related insulin resistance." (PMID 33647469, 2021). "In this study, we for the first time demonstrated that ILK in adipocytes is pivotal for regulating obesity-associated adipocyte hypertrophy and insulin resistance, but not inflammation." (PMID 33647469, 2021). "Moreover, our results suggest that the ECM-integrin-ILK pathway contributes to insulin resistance in mice, which may also apply to adipose tissue in morbidly obese humans." (PMID 33647469, 2021). "Interestingly, Wasserman's group found that improved insulin resistance was associated with an increase in CD31, a vascular/endothelial marker protein found in proximity to capillaries, implying increased signalling for local capillarisation in the HFD ILK‐deficient mice." (PMID 36054466, 2022).
atherosclerosis (8 papers, 2010 to 2025). A disease characterized by the build-up of fatty material and calcium deposition in the arterial wall resulting in partial or complete occlusion of the arterial lumen. "The RAGE/ILK/mTOR/p70S6K signalling pathway is another key player in the advancement of atherosclerosis, with ILK acting as a versatile intracellular serine/threonine kinase that contributes to the pathogenesis of the disease." (PMID 40959494, 2025). "ILK prevents endothelial dysfunction and the downstream cascade of events, including oxidative stress, hypertension, acute inflammation and atherosclerosis." (PMID 37452166, 2023). "The leading cause of ischaemia is coronary atherosclerotic disease and we have shown that ILK degradation in arterial endothelium induced during inflammatory conditions promotes atherosclerosis progression." (PMID 37452166, 2023). "Integrin-linked kinase (ILK) participates in the progression of cardiovascular diseases, such as endothelial dysfunction and atherosclerosis." (PMID 36139812, 2022). "Within this pathway, AGE activation triggers the expression of proteins in the ILK/mTOR/p70S6K signalling pathway, leading to VSMC-to-osteoblast trans-differentiation and cell proliferation, which in turn fosters the progression of atherosclerosis." (PMID 40959494, 2025). "Moreover, A recent study has shown that an increase in ILK expression coincides with higher rate of SMC migration within the atherosclerotic plaque in ApoE -/- mice, a reliable model that mimics the progression of atherosclerosis in humans." (PMID 20178627, 2010).
lung adenocarcinoma (8 papers, 2014 to 2023). A carcinoma that arises from the lung and is characterized by the presence of malignant glandular epithelial cells. "Taken together, our results suggest that the 3-gene signature of CTNNAL1 plus ILK plus KLF5 can be used to predict the outcome of patients with lung adenocarcinoma." (PMID 35154481, 2022). "In lung adenocarcinoma, as reported, ILK can regulate KRAS, IPP complex and Ras suppressor-1 (RSU1) to promote cancer cell multiplication, migration and epithelial-mesenchymal transition (EMT), and its high expression is pertinent to poor prognosis." (PMID 35029589, 2022). "Meanwhile, previous studies have indicated that modulating the ILK signaling pathway by PARVA made it more vulnerable to metastasis in lung adenocarcinoma." (PMID 29914539, 2018). "Importantly, we identify a CTNNAL1/ILK/KLF5 three-gene signature for predicting poor overall survival in patients with lung adenocarcinoma." (PMID 35154481, 2022). "ILK factors prominently in the progression of lung adenocarcinoma." (PMID 35804980, 2022). "A recent study reported that ILK promotes lung adenocarcinoma progression and metastasis through the regulation of KRAS, the IPP complex and RSU1, with other studies also linking ILK to cancer metastasis." (PMID 37568580, 2023). "ILK, together with PINCH1 and β-parvin (IPP complex), is overexpressed in human lung adenocarcinoma samples and in KRAS-driven disease in mice." (PMID 35804980, 2022). "A lentiviral-based shRNA was used to silence ILK genetically in the AGS, SNU-1, MKN45, and GES-1 gastric epithelial cells as well as in A549 and H1975 human lung adenocarcinoma cells, HK-2 human renal proximal tubular epithelial cells, and THP-1 human monocytic cells." (PMID 25398317, 2014).
osteosarcoma (8 papers, 2019 to 2023). A usually aggressive malignant bone-forming mesenchymal neoplasm, predominantly affecting adolescents and young adults. "Interleukin‐6 (IL‐6) activated the expression of ICAM‐1 and contributed to the migration of human osteosarcoma cells through integrin‐linked kinase (ILK)/Akt/AP‐1 pathways." (PMID 36772869, 2023). "According to the report, integrin-linked kinase (ILK) is a target gene of miR-542-3p in osteosarcoma, and upregulating miR-542-3p will downregulate ILK." (PMID 35427373, 2022). "For example, the downregulation of integrin-linked kinase (ILK) and integrin α6 by miR-542-3p and miR-127-3p, respectively, inhibits osteosarcoma cell proliferation, migration and invasion." (PMID 34884541, 2021). "MiR-542-3p and its target gene integrin linked kinase (ILK) in human osteosarcoma together with the differentially expressed genes from osteosarcoma tissues was analyzed through bioinformatics analysis in this study." (PMID 30636169, 2019). "A previous study demonstrated that the FN-αvβ3 integrin axis promotes tumor cell migration, invasion, and metastasis by upregulating the activity of integrin-linked kinase, which is an independent prognostic factor for poor survival of osteosarcoma." (PMID 30691475, 2019). "Some researchers have demonstrated miR-542-3p overexpression down-regulating ILK then inhibiting osteosarcoma has been verified." (PMID 35427373, 2022). "MiR‐542‐3p inhibits invasion and migration of esophageal cancer by repressing OTUB1, suppresses the proliferation of osteosarcoma via targeting Smad2, inhibits progression of oral squamous cell carcinoma by impeding ILK/TGF-β1/Smad2/3." (PMID 35427373, 2022). "overexpression of ILK is significantly correlated with distant metastasis and poor survival in patients with osteosarcoma, whereas downregulation of ILK significantly increases apoptosis and decreases angiogenesis and invasiveness of osteosarcoma cells." (PMID 32944406, 2020). "ILK promotes tumor proliferation and cell-cycle progression in many types of cancer, but its function in osteosarcoma is less clear." (PMID 30636169, 2019). "In our study, we studied the interaction between miR-542-3p and its target gene ILK, and further analyzed the influence of miR-542-3p and ILK on osteosarcoma." (PMID 30636169, 2019). "In this study, the influence of miR-542-3p and its target gene ILK on human osteosarcoma was observed." (PMID 30636169, 2019). "Real time quantitative polymerase chain reaction (qRT-PCR) and western blot showed that the miR-542-3p expression decreased while the ILK expression increased in the osteosarcoma tissues." (PMID 30636169, 2019). "In conclusion, miR-542-3p overexpression down-regulated its target gene ILK, promoted osteosarcoma cells apoptosis and inhibited their proliferation, migration and invasion." (PMID 30636169, 2019). "The results showed that ILK was up-regulated in osteosarcoma tissue and negatively correlated with miR-152-3p." (PMID 30636169, 2019). "In vivo experiments demonstrated that miR-542-3p overexpression considerably restrained the proliferation of osteosarcoma cells, which further verified that miR-542-3p suppressed osteosarcoma by targeting ILK." (PMID 30636169, 2019). "The results showed that ILK expression was much higher in osteosarcoma cells in comparison with normal cells (P<0.01)." (PMID 30636169, 2019). "To summarize, through qRT-PCR and western blot, the expression of miR-542-3p was down-regulated, while ILK was up-regulated in osteosarcoma tissues and cells." (PMID 30636169, 2019). "Two hits from our screen, PLK1 and ILK, have been reported to be oncogenes in osteosarcoma." (PMID 32944406, 2020). "Heat map was gained according to the results and ILK was up-regulated in human osteosarcoma." (PMID 30636169, 2019). "Furthermore, low expression of ILK inhibited the proliferation, apoptosis of osteosarcoma cells, as well as promoted cell migration and invasion." (PMID 30636169, 2019).
osteosarcoma (continued). "Through our experiments the overexpression of miR-542-3p could down-regulate its target gene ILK, thereby promote the apoptosis of osteosarcoma cells and inhibit migration, invasion and proliferation." (PMID 30636169, 2019). "Low expression of ILK promoted apoptosis and arrested cell cycle in osteosarcoma cells." (PMID 30636169, 2019). "Then we conducted the nude mouse transplantation tumor experiment to further analyze the influence of miR-542-3p and ILK on osteosarcoma, which may provide novelty insights into the treatment for osteosarcoma." (PMID 30636169, 2019).
renal cell carcinoma (8 papers, 2013 to 2024). "In 786-O renal cell carcinoma cells, OA activates integrin-linked kinase (ILK) via GPR40, resulting in the activation of Akt and COX-2 and subsequently promoting cell proliferation." (PMID 37373069, 2023). "LAMA4 overexpression induced cell migration in renal cell carcinoma via activation of the ILK/FAK/ERK pathway." (PMID 34414238, 2021). "Elevation of many integrin molecules may trigger metastasis in renal cell carcinoma, moreover, integrins also activate Akt via FAK, paxillin, and integrin-linked kinase." (PMID 38680858, 2024).
colitis (7 papers, 2011 to 2023). Inflammation of the colon. "When myeloid-ILK deficient mice along with the WT control mice were subjected to colitis-associated and APCmin/+-driven CRC, tumour burden was reduced by myeloid-ILK deficiency in both models." (PMID 38077324, 2023). "We have previously shown that myeloid-ILK deficiency reduced inflammation of experimental colitis by regulating neutrophil infiltration and cytokine production." (PMID 35692780, 2022). "ILK has been shown to promote inflammation and ILK KO in mouse intestinal epithelial cells display a reduction in inflammation of the colon (colitis) and inflammation-induced cancer (colitis-associated cancer)." (PMID 35692780, 2022). "Our laboratory has shown that myeloid-ILK-deficient cells in an experimental colitis model exhibited reduced activation of NF-κB and PI3K signaling pathway, but elevated STAT3 activation and proliferation of intestinal epithelium." (PMID 34163519, 2021). "We have also demonstrated that epithelial ILK deficiency leads to attenuation of DSS-induced colitis, an effect that was associated with a reduction in fibronectin expression, as well as an alteration in the ratios of lymphocyte populations." (PMID 24024606, 2013). "In both acute and chronic DSS-induced colitis, compared to wild-type mice, ILK-ko mice exhibit less weight loss, and have reduced inflammatory scores." (PMID 21806815, 2011). "Moreover, we have previously shown that myeloid-ILK deficiency reduced intestinal inflammation in experimental colitis by regulating neutrophil infiltration and cytokine production." (PMID 35692780, 2022). "Moreover, previous studies from our laboratory have shown that myeloid-ILK deficiency reduced intestinal inflammation in experimental colitis by regulating neutrophil infiltration and cytokine production." (PMID 34163519, 2021). "Since fibronectin is associated with colitis and its expression levels undergo biphasic modulation during induction of inflammation and during healing, we speculated that loss of ILK in epithelial cells may also have an impact on this protein." (PMID 21806815, 2011). "Moreover, the direct effects of fibronectin on Treg development provide a mechanism by which the loss of ILK in epithelial cells could lead to a reduced susceptibility to colitis." (PMID 21806815, 2011). "Others also demonstrate that inhibiting ILK abrogates NLRP3-mediated IL-1β production, that ILK knockdown reduces TNF-α production via NF-κB, and that ILK knockout in intestinal epithelial or myeloid cells reduces DSS-induced colitis in mice." (PMID 36930690, 2023). "Our earlier studies demonstrated that the myeloid-specific ILK is required for intestinal inflammation during DSS-induced colitis." (PMID 38077324, 2023). "We have previously uncovered a pro-inflammatory role for myeloid-specific ILK in dextran sodium sulfate (DSS)-induced colitis." (PMID 38077324, 2023). "We have previously shown that ILK expression in myeloid cells is involved in regulating neutrophil infiltration in experimental colitis in mice." (PMID 35692780, 2022). "Our laboratory has reported that ILK inhibition in a mouse model of colitis blocked NF-κB (IKK and p65) activation, and suppressed TNF-α, IL-6, and IL-1β production as well as infiltration of inflammatory cells." (PMID 34163519, 2021). "ILK regulates inflammation in the mouse model of experimental colitis, and regulates growth and proliferation in colitis-associated cancer (CAC)." (PMID 34163519, 2021). "In contrast to Myo1F, minimal changes in integrin-ανβ3 and ILK were displayed in the colonic mucosa of control WT and Myo1F−/− mice and both molecules were increased at similar extent after colitis induction in both animals." (PMID 30687322, 2018).